CTLA4 (cytotoxic T-lymphocyte associated protein 4)
Diseases named in the same sentence as CTLA4 in open-access papers (continued):
Sharing a sentence is not in itself a finding about the gene and the disease.
bladder cancer (124 papers, 2011 to 2025). "Despite the efficacy of immune checkpoints, including programmed cell death-1 (PD-1) and cytotoxic T-lymphocyte-associated protein 4 (CTLA-4), the effect of immunotherapy for bladder cancer remains unsatisfactory." (PMID 35069212, 2021). "The most attentive checkpoint targets in bladder cancer treatments are programmed cell death protein-1 (PD-1), programmed death ligand-1 (PD-L1) and cytotoxic T lymphocyte-associated protein 4 (CTLA-4)." (PMID 34805266, 2021). "The bladder cancer samples were divided into high risk group and low risk group based on the median risk score, and the results of IHC indicated the positive frequencies of CTLA4 and LAG3 were higher in patients in high risk group." (PMID 34026819, 2021). "One study found that increases in inducible costimulator (ICOS) have a dual role in autoimmunity and immunosuppression; this pathway resulted in a better anti-CTLA-4 response in bladder cancer patients." (PMID 40227644, 2025). "CTLA-4 protein levels are upregulated in muscle-invasive bladder cancer and the CTLA-4-disrupted T-cells had greater cytotoxic anti-tumor effects." (PMID 39857950, 2025). "The advent of ICIs has revolutionized bladder cancer management, with PD-1/PD-L1 and CTLA-4 inhibitors representing the most clinically validated immunotherapies." (PMID 40904451, 2025). "Research has suggested that disrupting the expression of CTLA-4 in peripheral blood CD8+ T cells can enhance the cytotoxic immune response against bladder cancer cells, exerting anti-tumor effects." (PMID 40511303, 2025). "ICIs targeting PD-1, PD-L1, and CTLA-4 have shown significant clinical efficacy in treating advanced bladder cancer." (PMID 37425564, 2023). "Bladder cancer is highly correlated with immunotherapy, including anti-PD-L1 and anti-CTLA4 becomes a hotspot in advanced BCa treatment." (PMID 35148766, 2022). "Except for traditional treatment using BCG bladder irrigation, recently, immunotherapy targeting immune checkpoints CTLA-4 and PD-1/PD-L1 has been applied to treat early-stage bladder cancer, achieving satisfactory clinical efficacy." (PMID 36408130, 2022). "In bladder cancer tissue elevated expression of immune checkpoint antigens such as programmed cell death protein-1 (PD-1; =CD279), its ligand, PD-L1 (=CD274), anti-cytotoxic T-lymphocyte associated antigen-4 (CTLA-4, =CD152), and B7-H3 (=CD276) was observed." (PMID 35563359, 2022). "Recent studies have shown that immunotherapies based on immune checkpoint blockage, such as anti-PD-1/PD-L1 and anti-CTLA-4 antibodies, have prominent efficacy against bladder cancer." (PMID 34868963, 2021). "Therapeutically, in vivo studies using mice bearing the murine bladder cancer cell line MB49 showed that systemic administration of CPI-1205 in combination with anti-CTLA4 resulted in better anti-tumor immunity compared with anti-CTLA4 single therapy." (PMID 33403469, 2021). "In the multifaceted immune regulation of bladder cancer, PD-1, PD-L1, and CTLA4 are the primary immune checkpoints." (PMID 33604353, 2020). "Cytotoxic T cell antigen-4 (CTLA-4) is reportedly involved in the development of bladder cancer (BC)." (PMID 33335608, 2020). "Anti-CTLA-4 can drive increased ICOS expression on T cells in clinical trials, and ICOS upregulation on peripheral T cells is correlated with clinical responses to anti-CTLA-4 in bladder cancer." (PMID 31843013, 2019). "Further analyses of publicly available databases, revealed that FGF-2-expressing bladder carcinomas carry fewer genetic alterations and they tend to express high levels of CTLA-4, PD-1 and PD-L1, which suggests immune blockade by checkpoint activation." (PMID 28515962, 2017). "One study demonstrated the feasibility of neoadjuvant treatment using ipilimumab (anti-CTLA4) prior to cystectomy for 12 patients harbouring bladder cancer." (PMID 25525464, 2014).
bladder cancer (continued). "In support of this view, bladder cancer patients receiving anti-CTLA4 therapy showed an increase in the ratio of effector to regulatory T cells as well as tumor antigen-specific CD4 T cells." (PMID 22013484, 2011). "While more studies are necessary to solidify our understanding of anti-CTLA-4 therapy in bladder cancer, there is promising evidence that these could make a difference in treating NMIBC." (PMID 40227644, 2025). "However, immune checkpoint inhibitors (ICIs) targeting cytotoxic T-lymphocyte-associated antigen-4 (CTLA-4) and programmed cell death-1 (PD-1) have shown promise in treating bladder cancer." (PMID 37425564, 2023). "We also evaluated the response of bladder cancer patients to PD-1 and CTLA4 blockers by IPS score." (PMID 37072750, 2023). "Thus, the TIDE algorithm showed that patients with CAF-risk bladder cancer were more likely to be unresponsive to anti-PD1 and anti-CTLA4 therapies in both the training and test groups." (PMID 37124542, 2023). "Novel combination of immunotherapy with targeted drugs, including programmed death-1 (PD-1) inhibitor, cytotoxic T lymphocyte-associated antigen-4 (CTLA-4) inhibitor and PARP Inhibitors and immunotherapy, can improve response and reduce resistance for patients with bladder cancer." (PMID 36368976, 2022). "Similarly to the TC-1/dCD80-1-induced tumors, anti-CTLA-4 administered as a single therapy reduced the progression of another tumor type, i.e., mouse bladder cancer induced by the MB49 cell line with low CD80 expression." (PMID 33923750, 2021). "The inhibition of another pivotal immune checkpoint, CTLA-4 (cytotoxic T cell antigen), may result in the mobilization of the immune system against bladder cancer and, among anti-CTLA-4 antibodies, the use of Ipilimumab and Tremelimumab has been discussed." (PMID 32392774, 2020). "Locally administered CTLA-4 blocking antibodies have also been assessed in several experimental tumor models, including transduced epithelial tumors, colon cancer, pancreatic cancer, and bladder cancer (unpublished data)." (PMID 27714433, 2017). "A possible explanation for poor prognosis of FGF-2 expressing bladder cancers is the association with epithelial to mesenchymal transition (EMT), high proliferation, low mutation load and high expression of CTLA-4, PD-1 and PD-L1, thus being more sensitive to immune checkpoint inhibition." (PMID 28978000, 2017). "As main immunotherapeutic options, programmed cell death 1 (PD1), PD1 ligand (PDL-1), and cytotoxic T-lymphocyte antigen 4 (CTLA-4) expression might be served as potential factors for individual selection of treatment with immune checkpoint inhibitors for bladder cancer patients." (PMID 37968767, 2023). "Finally, the m6A score may predict the efficacy of CTLA-4 immunotherapy in patients with bladder cancer, providing new insights that may guide individualized treatment of patients with bladder cancer." (PMID 34604051, 2021). "However, similar to human basal-like bladder cancer, murine tumors in our model displayed an upregulated expression of immunoinhibitory molecules such as CTLA-4, PD-L1 and IDO1 which can lead to cytotoxic resistance and tumor escape which was observed at 25 weeks." (PMID 31779626, 2019). "Studies have demonstrated their potential in bladder cancer treatment, as ATOR-1015 BsAb, a human CTLA-4 ˟ OX40 IgG-like BsAb, activates T cells, suppresses regulatory T cells, and reduces tumor growth in bladder cancer models." (PMID 39990653, 2025). "There is currently no FDA-approved CTLA-4 antibody for bladder cancer, which highlights the need for additional research to assess CTLA-4 blockade in UC." (PMID 38201559, 2023). "Although treatments for bladder cancer using antibody-based anti-PD-L1/PD1 and anti-CTLA-4 have shown to be clinically effective, they cannot currently satisfy the treatment needs of all patients, as most patients have exhibited a poor response to immunotherapy at various stages of bladder cancer." (PMID 35991125, 2022).
bladder cancer (continued). "Notably, PDLIM2 expression was strongly correlated with TIM-3 in bladder cancer and with PDCD1, CTLA4, GZMB, and LAG3 in KIRP." (PMID 35121770, 2022). "Indeed, blocking the CTLA-4 gene in CD8+ CTLs with elevated PD-1/CTLA-4 expression enhances IFN-γ production and cytotoxicity against bladder cancer cells." (PMID 34446084, 2021). "Besides, ERBB3, FGFR3, CTLA4, and LAG3 are also reported in some studies as potential therapeutic targets for bladder cancer." (PMID 34026819, 2021). "Though the signature was only significantly associated with ICI-related biomarkers like TNFRSF9, instead of CTLA4, LAG3, HAVCR2 and PDCD1, thus proving that the efficacy of immunotherapy still presents an underprivileged position within the treatment of bladder cancer." (PMID 34322391, 2021). "Treated with CTLA-4 blockade, ICOS expressed higher on CD4+ T cells from peripheral blood and tumor tissues of bladder cancer patients and this CD4+ICOShi T cell population produced higher IFN-γ, indicating that ICOS interacts with CTLA-4 and plays an important role in tumor immunity." (PMID 21917182, 2011). "There has not been significant exploration of anti-CTLA-4 inhibitors in bladder cancer." (PMID 40227644, 2025). "Excepting chemotherapy, immunotherapy is another important treatment for bladder cancer; in our study, we found that anti-CTLA4 and anti-PD1 were sensitive to patients with high-risk score of bladder cancer no matter whether used separately or in combination." (PMID 36131793, 2022). "However, administration of CTLA-4 antibodies did not downregulate the ratio of Treg cells in bladder cancer." (PMID 35069212, 2021). "While mice treated with anti-CTLA4 alone did not exhibit significantly decreased tumor growth compared to the control group, the combination of EC5026 and anti-CTLA4 treatment significantly suppressed MB49 bladder cancer tumor growth compared to control." (PMID 38330013, 2024).
pancreatic cancer (124 papers, 2011 to 2026). "In this study, we found that treatment with CIRT+HCQ was necessarily required for pancreatic cancer cells to become susceptible to anti‐CTLA4 Ab." (PMID 40230051, 2025). "The programmed death-1 (PD-1)/programmed cell death 1 ligand 1 (PD-L1) and cytotoxic T lymphocyte-associated antigen-4 (CTLA-4) immune checkpoints have gained considerable attention in the treatment of pancreatic cancer." (PMID 38756774, 2024). "This study aimed to enhance antitumor immune responses to pancreatic cancer via Ab-based blockade of IL-6 and cytotoxic T-lymphocyte–associated protein 4 (CTLA-4)." (PMID 36881480, 2023). "Treg cells secrete inhibitory cytokines such as TCF-β, CTLA4, IL-10, and PD-L1 to mediate the immune tolerance of the effective cell to pancreatic cancer associated antigen, thereby avoiding the tumor cells from immune surveillance." (PMID 37064113, 2023). "According to the results from GSE63557 dataset, we discovered that the pancreatic cancer patients with high-risk score response better to anti-CTLA-4 treatment." (PMID 37333498, 2023). "In patients receiving CTLA-4 inhibitors, there is still a trend towards an increased risk of adverse reactions with the use of aspirin, but only with statistical significance in pancreatic cancer (OR 2.91, 95% CI 1.71–4.96, FDR adjusted p = 0.002)." (PMID 38035011, 2023). "Another meta-analysis showed that the CTLA-4 +49A allele is associated with increased risk of pancreatic cancer in Caucasians and Chinese populations compared to the +49G allele." (PMID 33226370, 2020). "Pancreatic cancer has been unresponsive to both anti-programmed death 1 (anti-PD-1) and anti-cytotoxic T-lymphocyte-associated antigen 4 (anti-CTLA-4)." (PMID 31620245, 2019). "Up to date, the association studies have been performed for CTLA-4 A49G polymorphism with respect to several disease susceptibility, such as liver disease, pancreatic cancer, primary biliary cirrhosis, etc.." (PMID 25128482, 2014). "The results showed that COL10A1 was significantly correlated with PD-L1 and CTLA-4 in pancreatic cancer, suggesting that COL10A1 may be associated with immune escape." (PMID 36105715, 2022). "Finally, pancreatic cancer cells express cytotoxic-T-lymphocyte associated protein 4 (CTLA-4) and the ligand for programmed cell death protein-1 (PD-1), PD-L1, which is activated by the EGFR/MAPK pathway from myeloid cells, inhibiting T cell function." (PMID 30060755, 2018). "Similarly, no objective responses were seen in locally advanced or metastatic pancreatic cancer patients treated with cytotoxic T-lymphocyte associated protein 4 (CTLA-4) inhibitor monotherapy." (PMID 30294755, 2018). "In a pancreatic cancer mouse model, pharmacological macrophage depletion enhances tumor reduction induced by antibodies against T cell inhibitory receptors cytotoxic T-lymphocyte- associated antigen 4 (CTLA4) and programmed cell death protein 1 (PD1) that augment tumoricidal CD8 + T cell responses." (PMID 26275794, 2015). "Beyond PD1 and CTLA-4 blockade, many other immune checkpoints are under scrutiny as potential targets for future immunotherapy in pancreatic cancer." (PMID 39330013, 2024). "In this context, the use of combination therapy is currently preferred because of the immunosuppressive microenvironment of pancreatic cancer, which makes it often difficult to obtain optimal efficacy with CTLA-4 inhibitors alone." (PMID 38756774, 2024). "was that in our samples CD8+ cells expressed lower levels of CTLA-4 as compared to TLDNs in pancreatic cancer." (PMID 39474426, 2024). "Studies carried out on the effectiveness of ICI treatments involving the use of anti-PD-1 or anti-CTLA-4 antibodies in pancreatic cancer, both alone and in combination, have revealed unsatisfactory overall response rates of 0% and 3%, respectively." (PMID 38357542, 2024).
pancreatic cancer (continued). "For patients with advanced pancreatic cancer, the low-risk subgroup showed significantly higher IPS scores when treated with CTLA4 blockers alone or a combination of CTLA4 and PD1 blockers, compared to the high-risk group." (PMID 39867576, 2024). "Pancreatic cancer patients with low POSTN expression showed a better (predicted) response to CTLA4 and/or PD1 and PD‐L1 checkpoint inhibitors." (PMID 38389400, 2024). "To confirm these effects, we performed the correlation between tumoral ABHD17C and the efficacy of anti-PD1 therapy; We first searched for datasets of pancreatic cancer patients treated with Anti-PD1/CTLA-4/PD-L1." (PMID 37273016, 2023). "Patients with a lower m5Cscore exhibited more therapeutic efficiency on anti-CTLA4 therapy in liver cancer, while the combination of anti-CTLA4 therapy and pd1 was more efficient for patients with a lower m5Cscore in pancreatic cancer." (PMID 37332118, 2023). "Together, our findings suggest that combined blockade of IL-6 and CTLA-4 can regress pancreatic tumors via a potentially unique mechanism by imparting CD4+ and CD8+ T cell–mediated antitumor immunity." (PMID 36881480, 2023). "Targeting CD40 by agonistic mABs powerfully enhanced responses of both anti-PD1 and anti-CTLA4 therapies in an immunotherapy-resistant pancreatic cancer model." (PMID 37359522, 2023). "pointed out that having a higher CTLA4 on CD8+ T cells at the baseline (before treatment) predicted a poorer overall survival for pancreatic cancer patients." (PMID 37181043, 2023). "The cystine‐glutamate antiporter xCT protein SLC7a11 regulates cellular sensitivity to ferroptosis by regulating glutathione synthesis, and inhibition of SLC7a11 improves the efficacy of anti‐CTLA‐4 in the colon and pancreatic cancers." (PMID 37860928, 2023). "Even so, certain tumors have a significant and independent propensity to express high TIM‐3 transcript levels, including pancreatic cancer and tumors with high PD‐L1 and/or high CTLA‐4 transcript levels." (PMID 38132831, 2023). "Mice bearing s.c. or orthotopic pancreatic tumors were treated with blocking Abs to IL‐6 and/or CTLA-4." (PMID 36881480, 2023). "We find that TIM‐3 RNA expression is more common in pancreatic cancer and tumors exploiting PD‐L1 and CTLA‐4 checkpoints." (PMID 38132831, 2023). "CD40 antibodies have been shown in preclinical studies to improve responses to combinations of chemotherapy or radiotherapy with anti-PD1 and anti-CTLA4 in pancreatic cancer, one of the tumors most resistant to immunotherapy." (PMID 37620372, 2023). "The clinical efficacy of immune checkpoint blockade in pancreatic cancer targeting PD-1 and CTLA-4 has been modest, despite the remarkable success of ICB in treatment of patients with other solid tumor malignancies." (PMID 36302761, 2022). "We previously generated CyTOF data using PBMCs from patients with PDAC treated with ipilimumab, a checkpoint immunotherapy targeting CTLA-4, and a GM-CSF–secreting allogeneic pancreatic cancer vaccine (GVAX)." (PMID 36214223, 2022). "Checkpoint immunotherapies such as monotherapy and combination therapy utilizing anti-PD1 and anti-CTLA4 antibodies have been remarkably successful in other cancers but have been ineffective in pancreatic cancer." (PMID 36310582, 2022). "As a critical negative regulator, CTLA-4 limits immune responses of T cells to PDAC cells under the circumstances of pancreatic cancer, which provides a potential treatment option, that is, the CTLA-4 blockade." (PMID 34819086, 2021). "To predict the pancreatic cancer patients’ response to immunotherapy, we further investigated the difference in the expression of immune checkpoints (PD-1, PD-L1, CTLA-4, LAG3, TIGIT and TIM-3) between patients with low and high m6Ascore." (PMID 34332578, 2021). "Other CTLA-4 inhibitors like Tremelimumab and PD-1 inhibitors like Pembrolizumab and Atezolizumab have also been tested alone and in combination in advanced pancreatic cancer." (PMID 38107772, 2021).